CCL3 (C-C motif chemokine ligand 3)
Diseases named in the same sentence as CCL3 in open-access papers (continued):
Sharing a sentence is not in itself a finding about the gene and the disease.
cancer (continued). "However, even with these limitations, many of the findings discussed have been validated by the fact that the same chemokine systems appear to be involved in mediating bone metastasis regardless of the cancer of origin, in particular CCL2/CCR2, CCL3/CCR1, IL-8/CXCR1, and CXCL12/CXCR4." (PMID 29930538, 2018). "Because injections of CCL3 and CCL20 did not induce any detectable inflammatory response or liver injury in vivo (data not shown), we believe it is possible that CCL3 and CCL20 could be employed to efficiently recruit DC precursors for the purpose of DC-based cancer therapy." (PMID 20420712, 2010).
bacterial infection (21 papers, 2011 to 2026). "We have demonstrated that topical CCL3 treatment restores neutrophil influx, reduces bacterial infection by ~99%, and accelerates wound healing in diabetic mice." (PMID 41597195, 2026). "Analysis of proinflammatory cytokines and chemokines at different time points showed significant upregulation of Tnf, Mmp14, Il1b, Il1a, Il17ra, Cxcl1, Cxcl2, Ccrl2, Ccl3, Ccl4, and Ccl9 after bacterial infection." (PMID 41117166, 2025). "BMMs that are mobilized in response to bacterial infections within peripheral tissues are known to be potent inducers of pro‐inflammatory interferons (eg, IFNγ), as well as additional cytokines and chemokines such as IL‐1, IL‐18, Ccl3, Cxcl9, and others." (PMID 32841534, 2020). "Here, using mice infected by the intracellular bacterium Listeria monocytogenes, we show that during a recall bacterial infection, the chemokine CCL3 secreted by memory CD8+ T cells drives drastic modifications of the functional properties of several populations of phagocytes." (PMID 22241983, 2011). "The cytolytic granules have been shown to contain chemokines such as CCL3, CCL4 and CCL5 in addition to the classical mediators of cytotoxicity (GZMB, PRF1 and GNLY), in both viral and bacterial infections, indicating their role in cytolysis." (PMID 38501302, 2024). "Consistent with this, patients with amputations resulting from combat wounds showed increased serum levels of CCL3 and CCL4 as well as increased CXCL8, CCL3, and CCL4 in the wound effluent due to bacterial infection." (PMID 30340330, 2018). "Classical type 1 cytokines and chemokines (e.g., IL-2, IL-12, IFN-γ, TNF-α, MCP-1/CCL2, MIP-1α/CCL3, and RANTES/CCL5) were predominantly induced around the peak of bacterial infection, and then decreased as bacterial replication was controlled at 28 dpi." (PMID 27479584, 2016). "In conclusion, the multifunctional chemokines CCL3 and CXCL2 are produced locally in response to bacterial infection of bones." (PMID 24795505, 2014). "Systemic analysis of chemokines in combat wounds infected with <105 colony forming units (CFU) of bacteria were found to have increased serum levels of CXCL10, CXCL8, and CCL3 compared to combat wounds without bacterial infection." (PMID 30340330, 2018).
inflammation (18 papers, 2013 to 2024). Aberrant reaction of the microcirculation characterized by movement of fluid and leukocytes from the blood into extravascular tissues. "GM-CSF promotes the influx of myeloid cells, CCL2 is known to recruit monocytes, CCL3 has a role in lung inflammation and lymphocyte recruitment, and CCL7 can be linked to acute neutrophilic lung inflammation." (PMID 37600776, 2023). "This is illustrated by their strong expression of pro-inflammatory mediators including chemokines (e.g. Ccl3, Ccl4) and members of the IL-1 family, such as Il1f9 (encoding for IL-36γ) that was specifically expressed by neutrophils and recently identified as an amplifier of pulmonary inflammation." (PMID 38348034, 2024).
cardiovascular disease (6 papers, 2016 to 2026). "Previously, CCL3, 5 and 18 serum levels have been linked to cardiovascular disease (secondary events in early follow-up, refractory UAP, and ACS) and have been shown to be expressed by atherosclerotic plaque." (PMID 27573044, 2016). "Nonclassical CD 14+CD16++ monocytes are potent proinflammatory cells related to cardiovascular disease and substantially secrete inflammatory cytokines, like tumour necrosis factor-α, interleukin-1β, and CCL3." (PMID 29213284, 2017). "Previous studies on CCL3, 5 and 18 have focused on the post-ACS stage, pointing to different roles of CCLs with regard to cardiovascular disease." (PMID 27573044, 2016).
hematological malignancies (6 papers, 2018 to 2025). "Additional support for the feasibility of CCL3 inhibition as a therapy for hematologic malignancies is provided by the availability of inhibitors for CCL3 receptors." (PMID 30279500, 2018). "Our results demonstrate a previously unrecognized role of CCL3 in the maintenance of homeostatic hematopoiesis that should be evaluated when targeting CCL3 signaling for the treatment of hematologic malignancy." (PMID 30279500, 2018). "Therefore, CCL3 is an appealing therapeutic target in hematologic malignancies." (PMID 30279500, 2018). "Since therapeutic treatment of many hematologic malignancies requires a functional HSPC pool to reestablish hematopoietic homeostasis, it is critical that treatment, including CCL3 inhibition avoids reduction of HSPCs within the bone marrow." (PMID 30279500, 2018).
kidney diseases (5 papers, 2014 to 2022). "Several studies have reported the involvement of CCL3 in kidney diseases." (PMID 35743123, 2022). "Of note, in our kidney mRNA assessment, we did not see a significant change in Ccl3 or Cxcl2 mRNA changes; this likely reflects that kidneys lack cells similar to stellate cells and that renal disease in SCD is not characterized by inflammatory cell infiltrates." (PMID 33542720, 2020).
neurodegenerative disease (5 papers, 2017 to 2025). A disorder of the central nervous system characterized by gradual and progressive loss of neural tissue and neurologic function. "In neurodegenerative disease specimens, CCL3 is predominantly expressed by neurons." (PMID 40917546, 2025). "In degenerative diseases, upregulated CC chemokines MCP-1 (CCL2), MIP-1α (CCL3), and RANTES (CCL5) are possibly involved in the migration of endothelial progenitor cells during tissue repair, with MCP-1 and MIP-1α able to mobilize mesenchymal stem cells into ischemic brain lesions." (PMID 29109449, 2017).
adenocarcinoma (3 papers, 2020 to 2024). A common cancer characterized by the presence of malignant glandular cells. "In adenocarcinomas, the expression ratios (normal-to-pathological) of ACKR2 were positively correlated with all those chemokines while in polyps, with CCL3 and less markedly with CCL4 and CCL7." (PMID 33374792, 2020).
cardiac disease (3 papers, 2019 to 2023). "2. miR-103-3p → CCL3(−)→ decrease the risk of cardiac diseases." (PMID 37841310, 2023).
peripheral neuropathy (3 papers, 2017 to 2025). A disorder affecting the peripheral nervous system. "This section reviews studies linking CCL3 to neuropathic pain, with a focus on chemotherapy-induced peripheral neuropathy (CIPN)." (PMID 41153795, 2025). "This literature review aims to critically examine the role of CCL3 in CRC and chemotherapy-induced peripheral neuropathy (CIPN), with a focus on identifying potential mechanistic overlaps." (PMID 41153795, 2025). "The importance of CCL3 and CCL4 chemokine activity in the development and maintenance of neuropathic pain has been previously identified in several animal models of central and peripheral neuropathies." (PMID 28125674, 2017).
retinopathy (3 papers, 2016 to 2026). "In experimental oxygen-induced retinopathy, mice were treated with the combination therapy of Ccl3- and Ccl2-neutralising antibodies, rather than a singular therapy." (PMID 26911327, 2016).
metabolic disease (2 papers, 2013 to 2019). A congenital disorder (due to inherited enzyme abnormality) or acquired (due to failure of a metabolically important organ) disorder resulting from an abnormal metabolic process. "Moreover, CCL3−/− mice showed significantly reduced hepatic and serum triglyceride levels when compared to CCL3+/+ mice (P<0.05), suggesting that CCL3 might also operate in metabolic disease." (PMID 23799074, 2013).
vasculopathy (2 papers, 2022). "Histological analysis of affected tissues from mice treated with SSc PBMCs (SSc hu-mice) demonstrated substantial inflammation, fibrosis and vasculopathy with human immune cell infiltration and increased expression of IL-17, TGF-β, CCL2, CCL3, and CXCL9." (PMID 36175484, 2022).
hematologic cancer (1 paper, 2022). "Within the hematologic cancer patient cohort there was a striking increase in the levels of the chemokines CCL2, CCL3, CCL4, CXCL8, and the cytokine IL-1β, in the Severe-Death group compared to the Mild group." (PMID 36700209, 2022). "We also observed increased concentrations of CCL2, CCL3, CCL4, VEGFA and IL-1β in Severe-Death hematologic cancer patients." (PMID 36700209, 2022).
CCL3 also shares sentences with these, for which no sentence is quoted: acute respiratory distress syndrome (23 papers); gingivitis (8); endothelial dysfunction (7); chronic obstructive pulmonary disease (6); dermatitis (5); dry eye syndrome (5); lymphopenia (5); pulmonary TB (5); type 2 diabetes (5); uveitis (5); allergic asthma (4); bacteremia (4); bipolar disorder (4); cerebral malaria (4); clear cell renal cell carcinoma (4); falciparum malaria (4); fatty liver (4); infectious disease (4); Infertility (4); Multiple Organ Failure (4); neurological disease (4); nonalcoholic steatohepatitis (4); polycystic ovary syndrome (4); Thrombocytopenia (4); acute lymphoblastic leukemia (3); acute myocardial infarction (3); Allergy (3); autoimmune myocarditis (3); bacterial pneumonia (3); Brain atrophy (3).
A further 225 diseases each share a sentence with CCL3 in 3 papers or fewer.